ALB (albumin)
Diseases named in the same sentence as ALB in open-access papers (continued):
Sharing a sentence is not in itself a finding about the gene and the disease.
diabetic nephropathy (continued). "Increased urinary albumin excretion is a hallmark of glomerular disease including diabetic nephropathy." (PMID 25849723, 2015). "Urinary 8-OHdG did not improve the ability to determine which patients are at risk of progressive diabetic nephropathy over and above measuring urinary albumin to creatinine ratio." (PMID 26239462, 2015). "Dietary omega-3 fatty acid (FA) is associated with a slower deterioration of albumin excretion in patients with diabetic nephropathy and in model diabetic rats." (PMID 26089878, 2015). "Dietary omega-3 fatty acid (FA) has cardioprotective effect and is associated with a slower deterioration of albumin excretion in patients with diabetic nephropathy." (PMID 26089878, 2015). "Increased albumin excretion is not only a marker for early diabetic kidney disease but also for increased risk for macrovascular disease." (PMID 28702221, 2015). "Multiple prior studies have found independent associations of low serum albumin with disease progression outcomes among patients with diabetic nephropathy and CKD." (PMID 22719981, 2012). "Common pathological characteristics between human and animal models in the case of glomerular diseases, such as CGN and diabetic nephropathy, include urinary leakage of proteins, such as albumin (albuminuria), caused by disruption of the blood-urine barrier." (PMID 21304992, 2011). "Diabetic nephropathy is mainly associated with excess urinary albumin excretion, abnormal renal function as represented by an abnormality in serum creatinine." (PMID 16677399, 2006). "In a study investigating the relationship between blood pressure and diabetic kidney disease progression, Dillon found that mean serum albumin was associated with decline in GFR." (PMID 15985177, 2005). "Supporting this, other investigations have shown that low serum albumin levels may be associated with more advanced diabetic kidney disease." (PMID 41497728, 2025). "This study suggests that LRG1 may be associated with increased excretion of urinary albumin in the early stages of diabetic nephropathy." (PMID 37916147, 2023). "Our findings suggest, therefore, that LRG1 might be associated with increased excretion of urinary albumin in the early stages of diabetic nephropathy." (PMID 37916147, 2023). "Moreover, in diabetic nephropathy, Urinary exosomal levels of miR-15b-5p have been positively associated with urinary albumin-to-creatinine ratio, negatively associated with eGFR, and correlated with speedy failure in kidney function." (PMID 35586497, 2022). "Therefore, the latest diagnostic criteria for diabetic kidney disease (DKD) include low eGFR or the persistent presence of elevated urinary albumin excretion (albuminuria)." (PMID 34764941, 2021). "Kidney injury models such as 5/6 nephrectomy, adriamycin nephropathy, the MWF spontaneous albuminuria rat model, STZ diabetic nephropathy, aldosterone treatment, and the Zucker fatty rat obese model are characterized by glomerular endothelial glycocalyx shedding causing albumin leakage." (PMID 32870819, 2020). "One of the microvascular complications of DM is diabetic nephropathy (DN) or diabetic kidney disease, a syndrome characterized by the presence of pathological quantities of urine albumin excretion, diabetic glomerular lesions, and loss of glomerular filtration rate (GFR) in diabetics." (PMID 30719346, 2019). "It was also reported that low serum albumin was associated with a worse renal prognosis in a sub-analysis of the prospective, multinational, double-blind, randomized study in 1,513 patients with diabetic nephropathy." (PMID 29795559, 2018). "Many risk factors have already been associated with the development and progression of diabetic nephropathy, such as elevated HbA1c, duration of diabetes, presence of concomitant microvascular complications (especially retinopathy) and elevated albumin excretion rate." (PMID 29568334, 2018).
diabetic nephropathy (continued). "Urinary albumin excretion along with extracellular matrix accumulation, basement membrane thickening, mesangial hypertrophy, and glomerular epithelial cell (podocyte) loss within the glomeruli are characteristic pathological features of diabetic nephropathy." (PMID 28767064, 2017). "Although microalbuminuria is a widely used indicator for diabetic nephropathy, its diagnostic accuracy is limited by the fact that structural damage might precede albumin excretion." (PMID 28577020, 2017). "Diabetic nephropathy is caused mostly by cellular metabolic disorders due to hyperglycemia, which induce functional alterations in renal microvasculature, glomeruli and tubular epithelium and promotes urinary albumin excretions." (PMID 27721418, 2016). "In patients with diabetic nephropathy, glomerular miR-21 was positively associated with albumin-to-creatinine ratio, whereas loss of miR-21 resulted in accelerated glomerular damage and podocyte apoptosis in a murine model of diabetic nephropathy and TGF-β1 transgenic mice." (PMID 27610006, 2016). "Recent studies have shown that urinary excretion of podocyte proteins is an indicator of podocyte injury, and that podocyte abnormalities and elevated concentrations of Amadori-modified glycated albumin (AGA) are linked to the development of diabetic nephropathy and to each other." (PMID 24303153, 2013). "Indeed, low serum albumin reflects malnutrition-inflammatory states in itself and/or a complication of metabolic syndrome and diabetic nephropathy, which is significantly and independently associated with DR in Japanese study." (PMID 23226496, 2012). "Consequently, there is a pressing need to further explore the role of risk factors for abnormal urinary albumin excretion, which conceivably “gets the ball rolling” in the pathogenesis of diabetic kidney disease." (PMID 22958709, 2012). "Thus, the association between LRG1 level and urinary albumin excretion observed in our study might be partially accounted for by these factors, because these contribute to an increased risk of diabetic nephropathy as well." (PMID 37916147, 2023). "Albuminuria, a hallmark of diabetic nephropathy, reflects not only injury and dysfunction of the filtration apparatus, but is also affected by altered glomerular hemodynamics and hyperfiltration, as well as by the inability of renal tubular cells to fully retrieve filtered albumin." (PMID 36139492, 2022). "Diabetic nephropathy (DN) is the leading cause of renal disease in adults and is characterized by two distinct biomarkers; estimated glomerular filtration rate (eGFR) and urinary albumin excretion (often assessed as albumin to creatinine ratio (UACR) ≥30 mg/g in a urine spot test)." (PMID 28645281, 2017). "Our study revealed that MLT alleviated disturbances in autophagy and oxidative stress in the kidneys of diabetic mice and in cells stimulated with albumin in anin vitro diabetic kidney disease model." (PMID 40509901, 2025). "Earlier research has indicated that Rb1 can alleviate urinary albumin elevation and renal tissue pathology in diabetic kidney disease (DKD) and unilateral ureteral obstruction (UUO)." (PMID 40682486, 2025). "Matrix metallopeptidase 9 (Mmp9)-mediated Sdc4 shedding leads to glomerular endothelial glycocalyx damage and increased albumin permeability, exacerbating the development of diabetic kidney disease (DKD)." (PMID 40180176, 2025). "Patients on HHD were younger, had diabetic nephropathy and nephroangiosclerosis as primary kidney disease less often, had lower Charlson comorbidity index and higher serum albumin indicating a better overall health status compared with IHD and PD." (PMID 39968507, 2025). "Proteinuria-induced damage to renal tubular epithelial cells is one of the main causes of diabetic kidney disease (DKD), and the clearance of overloaded albumin by lysosomes is crucial for maintaining the homeostasis of renal tubular epithelial cells." (PMID 40509901, 2025).
diabetic nephropathy (continued). "PNI (albumin + lymphocyte count) was originally used to assess nutritional status in gastric cancer and has since been applied to cervical cancer, diabetic nephropathy, and cognitive decline in the elderly." (PMID 41189897, 2025). "In our study, patients with diabetic kidney disease and positive H. pylori showed a significant reduction in the Albumin-to-Creatinine Ratio (ACR) from baseline levels after 3 months of treatment with either vonoprazan or lansoprazole." (PMID 41271916, 2025). "The diagnosis of diabetic nephropathy is determined by 24-hour urinary albumin excretion and serum creatinine levels." (PMID 39951451, 2025). "Another study found that extracellular vesicles from albumin-induced tubular epithelial cells promote M1 macrophage polarization by targeting Klotho, accelerating the progression of diabetic kidney disease." (PMID 40534860, 2025). "It is worth noting that diabetic kidney disease, which is manifested by continuous albumin presence in the urine and/or a steady decrease in glomerular filtration rate, affects 25%–40% of diabetic patients and emerges as the primary reason for ESKD globally." (PMID 40356408, 2025). "Albuminuria is a sensitive biomarker of kidney dysfunction, and the albumin/creatinine ratio (ACR) is an essential measure for monitoring diabetic kidney disease (DKD)." (PMID 40968851, 2025). "Diabetic kidney disease (DKD) is characterized by increased levels of albumin in the urine, decreased glomerular filtration rate (GFR), or a combination of both." (PMID 40149650, 2025). "We reported the importance of urinary angiotensinogen as an early marker for the onset of diabetic nephropathy and showed that it increases more sensitively than urinary albumin." (PMID 40003909, 2025). "In a multiple regression analysis (model 1), age, BMI, diabetic nephropathy, peripheral neuropathy, hemoglobin, serum albumin, eGFR, and SMI were significant explanatory variables for PhA." (PMID 40786473, 2025). "Urinary albumin determination, essential for determining the stage of diabetic nephropathy, resulted in a sensitivity of 100% and a specificity of 58.6%." (PMID 39810396, 2025). "Diabetic nephropathy in its earliest stages presents with low levels of albumin in urine, known as microalbuminuria, thus being a reliable indicator for diabetic nephropathy." (PMID 40978922, 2025). "Specifically, for every 10 g/L increase in ALB, the HRs for diabetic nephropathy, ophthalmopathy, and neuropathy were 0.42 (95% CI: 0.30–0.58), 0.61 (95% CI: 0.52–0.72), and 0.67 (95% CI: 0.51–0.88), respectively." (PMID 40391336, 2025). "The presence of microalbuminuria is a critical early indicator of diabetic nephropathy, reflecting the onset of glomerular injury and increased permeability to albumin." (PMID 40734849, 2025). "The results showed a sensitivity of 100% and a specificity of 58.6% in determining albumin in urine, which is important for determining the stage of diabetic nephropathy." (PMID 39810396, 2025). "These combined effects weaken the integrity of the glomerular filtration barrier, facilitating albumin leakage and proteinuria, which are hallmarks of diabetic kidney disease progression." (PMID 40171201, 2025). "The PSMA6 rs1048990G allele was linked to increased prevalence of diabetic kidney disease (DKD; OR = 1.75, 95% CI 1.02–2.99; p = 0.042), and the PSMD3 rs3087852A allele was associated with lower urinary albumin excretion." (PMID 41441015, 2025). "YMP significantly ameliorates diabetic nephropathy by reducing polyuria, proteinuria, albuminuria, and restoring serum albumin levels." (PMID 40810072, 2025). "The classical presentation and evolution of DN is characterized by impaired glomerular filtration membrane barrier function in patients with diabetic nephropathy leads to increased excretion of albumin in urine." (PMID 38357745, 2024).
diabetic nephropathy (continued). "Urinary albumin values are a crucial factor in determining the prognosis of diabetic nephropathy, and approximately 30 years after these reports, RAS inhibitors have been continuously prescribed with the aim of preventing kidney complications." (PMID 39031296, 2024). "The usual screening of diabetic nephropathy uses the albumin/creatinine ratio, which is normal at <30 mg." (PMID 38541098, 2024). "As urine albumin serves as a marker for glomerular function, its detection indicates a stage of diabetic nephropathy where the glomerulus is already compromised." (PMID 39131026, 2024). "A research team at Kanazawa University indicated that biopsy-proven diabetic nephropathy cases with increased urinary albumin levels displayed significant deterioration in kidney function." (PMID 39031296, 2024). "-Reduced urinary albumin and attenuated the progress of diabetic nephropathy via activation of renal AMP-activated protein kinase." (PMID 39768655, 2024). "OA was able to inhibit diabetic nephropathy via a reduction of the level of renal N-(carboxymethyl) lysine, HbA1c, urinary albumin, and urine glycated albumin, as well as increasing the level of plasma insulin and renal creatinine clearance." (PMID 38398510, 2024). "Diabetic kidney disease begins with microalbuminuria [urinary albumin excretion (UAE) < 300 mg per 24 h], followed by macroalbuminuria (UAE > 300 mg per 24 h), and then gradual loss of kidney function." (PMID 39456664, 2024). "A meta-analysis concluded that the combination of a-LA and valsartan significantly lowered urinary albumin levels and oxidative stress, boosted antioxidant capacity, and mitigated renal function damage in patients with diabetic nephropathy." (PMID 38671903, 2024). "Regarding the method used to screen for diabetic nephropathy, 200 physicians (85.5%) use the albumin-to-creatinine ratio, which is recommended by the guidelines as a measure for screening diabetic nephropathy." (PMID 38541098, 2024). "Diabetic nephropathy (DN), defined as continuously elevated urinary albumin and a diminished estimated glomerular filtration rate, is a serious complication of both type 1 diabetes and type 2 diabetes and is the main cause of end-stage kidney disease." (PMID 38931271, 2024). "Diagnosis of diabetic nephropathy was determined with the presence of a severely increased albumin-to-creatinine ratio (ACR) (i.e., >30 mg/g)." (PMID 38790911, 2024). "The promotion of interventions focusing on urinary albumin is correct and has contributed to improving the prognosis of diabetic nephropathy." (PMID 39031296, 2024). "Diabetic kidney disease is defined as albuminuria (albumin excretion rate > 300 mg/24 h) and declining renal function in a patient with known DM in the absence of urinary tract infection or any other renal disease." (PMID 39502964, 2024). "Diabetic nephropathy, commonly referred to as diabetic kidney disease, is a common issue characterized by elevated excretion of albumin in urine and diminished glomerular filtration rate resulting from abnormalities in the glomerulus." (PMID 38558585, 2024). "It is worth noting that some studies have also reported that tripterygium glycosides has no definite efficacy on reducing serum creatinine, urea nitrogen and increasing blood albumin in diabetic nephropathy." (PMID 39898319, 2024). "Diabetic kidney disease (DKD) is defined as chronic kidney disease induced by diabetes characterized by increased urinary albumin excretion and progressive reduction in renal function." (PMID 38217017, 2024). "Although higher pulse pressure in this study was more pronounced in individuals with diabetic nephropathy, it was also found in participants with a normal albumin excretion rate compared to controls." (PMID 39175027, 2024).
diabetic nephropathy (continued). "Exendin 4, administered for 8 weeks to C57BL/6J mice fed a high-fat diet and that were injected with streptozotocin, reduced urinary albumin and attenuated the progress of diabetic nephropathy via activation of renal AMP-activated protein kinase." (PMID 39768655, 2024). "Diabetic kidney disease refers to a persistently elevated urinary albumin-creatinine ratio (uACR ≥30 mg/g) or reduced estimated glomerular filtration rate (eGFR <60 mL/min/1.73 m2)." (PMID 39329106, 2024). "Another study found improved urinary-albumin-to-creatinine ratio, as well as improved glomerular filtration rate, in subjects with diabetic nephropathy who received supplementation with 360 mg magnesium from 2.25 g magnesium citrate." (PMID 39051301, 2024). "Diabetic kidney disease is clinically defined by decreased glomerular filtration rate (GFR) or elevated urinary albumin excretion (UAE), or both." (PMID 37545693, 2023). "The novel inflammatory predictor, such as C-reactive protein to serum albumin ratio, is higher in diabetic nephropathy." (PMID 37612612, 2023). "Clinically, the stage of diabetic nephropathy is primarily determined based on the urinary albumin excretion rate, glomerular filtration rate, creatinine, and total urinary protein." (PMID 38130399, 2023). "DKD was previously known as diabetic nephropathy (DN) and is defined as elevated urine albumin excretion, decreased glomerular filtration rate (GFR), or both." (PMID 36835159, 2023). "N-acetylcysteine (NAC) slightly reduces albumin/creatinine ratio and suppresses renal fibrosis in diabetic nephropathy in diabetic rat models." (PMID 37744367, 2023). "In diabetic kidney disease, a rise in blood pressure typically occurs early in the clinical course, around the same stage when albumin first appears." (PMID 38192517, 2023). "In humans with diabetic nephropathy, the urinary ALB was related to urinary TF, and urinary TF significantly increased with respect to the progression of glomerular diffuse lesions." (PMID 36855344, 2023). "The study’s findings also affirm the importance of urine albumin assessment in early diabetic nephropathy diagnosis." (PMID 37868453, 2023). "It is postulated that VEGF-A is involved in the pathogenesis of diabetic nephropathy (DN); however, its actual role is unclear, indicating its adverse effect on the permeability of the glomerular filter for albumin and a beneficial effect on others." (PMID 37834118, 2023). "Next, we examined glomerular urinary albumin levels, which indicate the total amount of albumin leaked from the glomerulus and are a typical marker of diabetic nephropathy." (PMID 36787192, 2023). "The diabetic control rats showed a marked reduction in albumin, globulin and total protein content because of micro proteinuria and albuminuria that are key markers of diabetic nephropathy." (PMID 37110767, 2023). "Serum albumin level has been reported to be independently related to renal prognosis in patients with diabetic kidney disease." (PMID 38156280, 2023). "It is possible to classify diabetic kidney disease according to urinary albumin excretion and the degree of renal dysfunction." (PMID 37370958, 2023). "The addition of niclosamide to patients with diabetic kidney disease receiving an angiotensin-converting enzyme inhibitor significantly reduces albumin excretion." (PMID 36793092, 2023). "In the early phase of the disease, the hyperfiltration phase and accompanying increased albumin excretion are characteristic features of diabetic nephropathy." (PMID 37370958, 2023). "The baseline characteristics showed that hemoglobin, serum albumin, and eGFR were significantly lower and serum urea nitrogen and serum creatinine were higher in diabetic nephropathy patients compared to healthy subjects (p < 0.01 for all)." (PMID 37511118, 2023).